HNF4G (hepatocyte nuclear factor 4 gamma)
Diseases named in the same sentence as HNF4G in open-access papers (continued):
Sharing a sentence is not in itself a finding about the gene and the disease.
bladder tumor (2 papers, 2015 to 2017). "HNF4G is a transcription factor responding to nutrient signals, and its overexpression in bladder tumors can significantly increase tumor cell viability, colony formation rate, and invasion, while HNF4G knockdown can achieve the reverse effects." (PMID 28252667, 2017). "This study explored the regulative role of miR-34a on an orphan nuclear receptor HNF4G, which has a well-confirmed role in bladder tumor growth and invasion." (PMID 25878394, 2015). "Our study confirmed the oncogenic role of HNF4G in bladder tumor." (PMID 25878394, 2015).
lung adenocarcinoma (2 papers, 2023 to 2024). A carcinoma that arises from the lung and is characterized by the presence of malignant glandular epithelial cells. "HNF4G expression was detected in the lung adenocarcinoma cell lines after treatment with various concentrations of cisplatin." (PMID 36923501, 2023). "This study aimed to look into the roles and mechanisms of HNF4G in cisplatin resistance of lung adenocarcinoma." (PMID 36923501, 2023). "According to the findings, HNF4G significantly increased the drug resistance of lung adenocarcinoma cells to cisplatin." (PMID 36923501, 2023). "In cell lines, high expression of HNF4G was significantly positively correlated with cisplatin resistance, and lung adenocarcinoma patients who had high HNF4G expression had a poor prognosis." (PMID 36923501, 2023). "Our findings also confirmed that HNF4G promotes the Akt signaling pathway, and we further revealed that HNF4G activates the Akt signaling pathway in lung adenocarcinoma by increasing MAPK6 expression." (PMID 36923501, 2023). "Meanwhile, the RNA-Seq data from the TCGA database revealed that the expression of HNF4G was significantly positively correlated with the expression of MAPK6 in patients with lung adenocarcinoma, also indicating that HNF4G regulates the expression of MAPK6." (PMID 36923501, 2023). "In this research, we discovered that a transcript factor, hepatocyte nuclear factor 4 gamma (HNF4G), significantly increases cisplatin’s resistance in lung adenocarcinoma by upregulating the MAPK6/Akt signaling pathway." (PMID 36923501, 2023). "We demonstrated the role of HNF4G in cisplatin resistance in lung adenocarcinoma in this study." (PMID 36923501, 2023). "We then examined the expression of HNF4G in the lung adenocarcinoma cell lines A549 and HCC827 after treatment with different concentrations of cisplatin using qRT-PCR and western blot, and discovered that it was significantly increased after cisplatin treatment." (PMID 36923501, 2023). "Further, a 2023 study demonstrated hepatocyte nuclear factor 4 gamma (HNF4G) binds to the ERK3 promoter and increases ERK3 protein level, increases AKT phosphorylation at S473 and reduces cisplatin sensitivity in lung adenocarcinoma cells." (PMID 38611058, 2024). "Based on the findings, we first discovered that HNF4G promotes MAPK6 expression and subsequent Akt phosphorylation by binding to the MAPK6 promoter region, resulting in cisplatin resistance in lung adenocarcinoma." (PMID 36923501, 2023). "By binding to the MAPK6 promoter region, HNF4G promotes MAPK6 expression and subsequent Akt phosphorylation, resulting in resistance to cisplatin in lung adenocarcinoma." (PMID 36923501, 2023). "HNF4G promotes MAPK6 expression and subsequent Akt phosphorylation by binding to the MAPK6 promoter region, resulting in resistance to cisplatin in lung adenocarcinoma." (PMID 36923501, 2023).
maturity onset diabetes (2 papers, 2019 to 2024). "There was enrichment in the pathways involved in beta-cell development (P = 0.02) and maturity onset diabetes of the young (P = 0.02) due to the inclusion of PDX1 and HNF4G." (PMID 39002386, 2024). "Firstly, as HNF4G is not expressed in pancreatic tissue according to The Human Protein Altas, we selected HNF4A (hepatocyte nuclear factor 4) because of its crucial role in pancreatic β-cells development and since its mutations cause a type of maturity-onset diabetes of the young." (PMID 31443431, 2019).
acute myeloid leukemia (1 paper, 2021). Acute myeloid leukemia (AML) is a group of neoplasms arising from precursor cells committed to the myeloid cell-line differentiation. "By computing zFPKM to define active gene expression, we observed that HNF4G, identified in acute myeloid leukemia, is not expressed and therefore likely to be a false positive." (PMID 34313788, 2021).
adrenal hypoplasia (1 paper, 2015). "Included in this group were AR, Coup-TFα, Coup-TFβ, dosage-sensitive sex reversal-adrenal hypoplasia congenital critical region on the X chromosome, gene 1 (DAX1), ERα, ERRα, HNF4γ, liver receptor homolog-1 (LRH1), NOR1, NURR1, PPARγ, RARβ, RORα, RORβ, and VDR." (PMID 26244663, 2015).
colon adenocarcinoma (1 paper, 2021). "In contrast, colon adenocarcinoma showed a significant enrichment of TFs such as CDX2 (26.5%), CDX1 (24%), HOXA13 (22%), HNF4G (37.2%), and TCF4 (36%) in gained peaks; and FOS::JUNB (45.4%), FOS::JUND (47.5%) and JUNB (46.3%) in lost peaks." (PMID 34090364, 2021).
colon cancer (1 paper, 2023). "Indeed, HNF4G expression, not HNF4A, correlated with BTNL3/BTNL8 expression and γδ T-cell infiltration into tumors in our human colon cancer dataset." (PMID 37309673, 2023).
glioma (1 paper, 2021). A benign or malignant brain and spinal cord tumor that arises from glial cells (astrocytes, oligodendrocytes, ependymal cells). "The combination of simultaneous knockdown of RPL32P3, YBX2, and HNF4G with DOX significantly induced U251 glioma cells apoptosis and produced the strongest effects." (PMID 34819492, 2021). "The simultaneous knockdown of RPL32P3, YBX2, and HNF4G combined with doxorubicin (DOX) increased the apoptosis of glioma cells." (PMID 34819492, 2021). "In this study, by establishing the BTB model in vitro, we found that the simultaneous knockdown of RPL32P3, YBX2, and HNF4G combined with DOX could significantly increase the apoptosis rate of glioma cells." (PMID 34819492, 2021). "The results suggested that the combined application of knockdown of RPL32P3, YBX2, and HNF4G could promote the passage of DOX through BTB and enhance the inhibitory effect of DOX on glioma cells." (PMID 34819492, 2021).
Obesity (1 paper, 2017). Accumulation of substantial excess body fat. "Meanwhile, in a GWAS study including up to 263,407 European individuals, an SNP near HNF4G (rs4735692) was found to be associated with clinical classes of obesity." (PMID 28460474, 2017).
pancreatic ductal adenocarcinoma (1 paper, 2021). An infiltrating adenocarcinoma that arises from the epithelial cells of the pancreas. "In pancreatic ductal adenocarcinoma, the role of HNF4G overexpression in promoting metastasis may be through regulating the cell-cell junction pathway." (PMID 34819492, 2021).
tumor (23 papers, 2015 to 2025). "Increased HNF4G are correlated with SMAD4 deficiency in PDAC tumor samples and associated with metastasis and poor survival time in xenograft animal model and in patients with PDAC (log-rank P = 0.036; HR = 1.60, 95% CI = 1.03–2.47)." (PMID 32737864, 2021). "HNF4G expression level was associated with tumor size and overall survival rate." (PMID 29719587, 2018). "To understand how a functional switch occurs from HNF4G-dependent state to a FOXA1-mediated metastatic state in the transition from primary tumor growth to metastatic progression, we explored our engineered human cancer cell line xenograft models." (PMID 41168397, 2025). "In the primary tumor context, we consistently find that the dominant transcription factor is HNF4G, where it functions as the driver." (PMID 41168397, 2025). "miR-34a, which acts as a tumor suppressor, reduces the expression of HNF4G by binding to its 3′-UTR, promoting its degradation through the RISC pathway." (PMID 40806474, 2025). "The increase in HNF1A and HNF4G protein after enzalutamide treatment was also observed by IHC of tumor samples." (PMID 40553565, 2025). "Hnf4g Hi-ChIP revealed elevated and preferential long-range looping in the primary tumor context compared to metastasis." (PMID 41168397, 2025). "We observed a substantial survival advantage of 19 days in HNF4G-KO tumor-bearing mice (P < 0.03) that were treated with GSK3368715." (PMID 41168397, 2025). "In the primary tumor context, HNF4G was the dominant transcription factor that drives tumor growth, while also negatively regulating FOXA1 transcriptional activity." (PMID 41168397, 2025). "Our data suggest that multiple mechanisms exist for a tumor to inhibit HNF4G activity, allowing FOXA1 to become active and drive metastatic spread." (PMID 41168397, 2025). "A comparison of HNF4G ChIP–seq from normal adjacent tissue showed that tumor-specific enhancers were occupied by HNF4G." (PMID 41168397, 2025). "FOXA1-OE did not change primary tumor growth in vivo compared to control mice, whereas HNF4G deletion had a substantial impact on primary tumor growth." (PMID 41168397, 2025). "Both HNF4A and HNF4G were reduced in tumor tissue from both datasets, mirroring reduced BTNL3 and BTNL8 expressions in human tumors." (PMID 37309673, 2023). "We compared HNF4A and HNF4G expressions between normal human colon and tumor tissues in the TCGA and Skrzypczak datasets." (PMID 37309673, 2023). "We also observed increased motif accessibility for the hepatocyte nuclear factors (HNF4A and HNF4G) in the Epi-H tumor clusters." (PMID 36973268, 2023). "In vivo experiments showed that treatment with Metformin of mice carrying PDAC xenograft derived from HNF4G-overexpressing T3M4 cells in the pancreas significantly reduced the tumor burden and prolonged survival time compared with treatment with vehicle." (PMID 32737864, 2021). "We then explore the effect of HNF4G on the capabilities of in vitro migration and invasion and in vivo metastasis in xenograft tumor models by stable overexpression or knockout of this gene in PDAC cells." (PMID 32737864, 2021). "Combined analysis of PDAC data in both The Cancer Genome Atlas (TCGA) and the genotype-tissue expression (GTEx) also showed significantly higher HNF4G RNA levels in tumor than in normal samples (P < 0.001)." (PMID 32737864, 2021). "IHC staining of tissue arrays showed that HNF4G expression levels were significantly higher in PDAC tumor than in adjacent normal tissues (P < 0.0001)." (PMID 32737864, 2021). "We have verified for the first time that HNF4G overexpression can be caused by the deficiency of SMAD4, a tumor suppressor gene that is frequently deleted or mutated in PDAC." (PMID 32737864, 2021). "Several studies have indicated that miR-34a modulates the migration and invasion of tumor cells by down-regulating hepatocyte nuclear factor 4 gamma (HNF4γ) and Notch1." (PMID 33221743, 2020).
tumor (continued). "In other 32 cases, less than 20% of tumor cells were positively stained, which were defined as HNF4G low expression group." (PMID 29719587, 2018). "We then analyzed the relation between HNF4G protein expression and clinicopathological features, and found that higher expression of HNF4G was correlated with larger tumor size and poorer overall survival." (PMID 29719587, 2018). "More than 20% of tumor cells were positively stained in 53 cases, which were defined as HNF4G high expression group." (PMID 29719587, 2018). "Equal amount of H358 cells were subcutaneously injected into nude mice, and after tumor formation, the nude mice were intravenous injected with HNF4G siRNA-2 or siNC." (PMID 29719587, 2018). "A slower tumor growth rate was observed in mice injected with HNF4G siRNA-2 as compared with mice injected with siNC." (PMID 29719587, 2018). "miR-34a can directly downregulate the expression of HNF4G and thus inhibit tumor cell viability, colony formation, and invasion." (PMID 25878394, 2015). "FOXA1-OE was unable to reverse the tumor growth retardation resulting from the deletion of HNF4G, suggesting that HNF4G is the dominant transcription factor in the primary tumor context, whereas FOXA1 appears to lack any tumor-promoting activity in this context." (PMID 41168397, 2025). "Thus, HNF4G can induce chromatin opening at the target genes that are consistently expressed in patient primary tumor samples, but these genes are decreased in expression in metastases, mimicking the expression profile of HNF4G mRNA." (PMID 41168397, 2025). "Using unsupervised hierarchical clustering, the HNF4G target genes (discovered in our orthotopic tumor experiments) were specifically expressed in primary tumors, as opposed to metastatic samples, implying that the HNF4G target genes were restricted to primary tumor contexts." (PMID 41168397, 2025). "The HNF4G-KO resulted in slower tumor growth compared to control (Cas9) tumors (P < 0.0001) and substantially smaller tumors, confirming that HNF4G is required for optimal tumor growth." (PMID 41168397, 2025). "We sought to explore the role of HNF4G in more complex tumor models of human disease." (PMID 41168397, 2025). "To determine whether the restoration of HNF4A, HNF4G, and Btnl1 expression in tumors from VA;Bcl9F/F;Bcl9lF/F mice affected tumor-infiltrating γδ T cells, we quantified these cells in tumor tissue." (PMID 37309673, 2023). "HNF4G primarily promotes tumor progression, according to numerous other studies." (PMID 36923501, 2023). "The expression level of HNF4G is related to the tumor size and overall survival rate." (PMID 35013450, 2022). "In addition, multiple hepatocyte nuclear factors (e.g., HNF1A, HNF4A, and HNF4G) we identified in tumor cells have been shown to be specific for proximal tubule cells, which are the original cells of ccRCC79." (PMID 35853872, 2022). "Furthermore, we found that the elevated HNF4G RNA levels were significantly correlated with advanced tumor stage (P = 0.008) and poor survival (HR = 1.60, 95% CI = 1.03–2.47)." (PMID 32737864, 2021). "Several studies have indicated that miR-34a suppressed the migration and invasion of tumor cells by down-regulating HNF4γ and Notch1, consistent with our hypothesis that DNMT3B may play its role by miR-34a-HNF4γ and/or Notch1 axis." (PMID 33221743, 2020). "The expression of HNF4G protein was correlated with the tumor size and the prognosis of patients." (PMID 29719587, 2018). "Consequently, the binding motif of Hnf4g is the most significantly enriched transcription factor motif in the promoters of genes that are specifically upregulated in those tumor cells that lack a CSC phenotype (Fig EV4B)." (PMID 29945941, 2018). "Functional study showed that miR-34a-HNF4G axis could modulate tumor cell viability, colony formation rate, and invasion." (PMID 25878394, 2015).
tumor (continued). "HNF4G overexpression could significantly increase tumor cell viability, colony formation rate, and invasion, while HNF4G knockdown could achieve reverse effects in in vitro model." (PMID 25878394, 2015). "Therefore, while HNF4G is the dominant transcription factor in primary tumor contexts, a switch occurs in advanced disease, resulting in engagement of FOXA1 to enhancers that create spatial genomic re-organization and ultimately in induction of metastasis-specific gene targets." (PMID 41168397, 2025). "These HNF4G-restricted FOXA1 metastasis genes were correlated well with the gene expression profiles of metastatic patient samples (mets) when compared to a cohort of classical subtype primary tumor samples (from the PanCuRx dataset), validating the conclusion from the preclinical models." (PMID 41168397, 2025). "We then explored whether HNF4G-siRNA-2 was able to inhibit tumor growth in vivo." (PMID 29719587, 2018). "In addition, HNF4G siRNA reduced cell proliferation in a xenograft tumor-bearing model." (PMID 29719587, 2018). "miR-34a could suppress tumor cell proliferation and invasion through suppressing HNF4G expression." (PMID 25878394, 2015). "To date, our data suggest that HNF4G is the primary driver of tumor growth, whereas FOXA1 becomes the driver of metastasis, and together, they both contribute to tumor progression and overall survival." (PMID 41168397, 2025). "Our data so far suggest that HNF4G can cobind with FOXA1 to the same genomic regions, but only HNF4G is essential for tumor growth, in part, by recruitment of PRMT1." (PMID 41168397, 2025). "Overall survival is influenced by HNF4G and FOXA1 activity in primary tumor growth and in metastasis, respectively." (PMID 41168397, 2025). "Nuclear receptors RORa, NR2F6 and HNF4G are uncovered as candidate transcriptional drivers of these cells whilst closure of binding sites for E2F2 and E2F4 indicate post-treated tumour having low proliferative capacity." (PMID 39341888, 2024). "HNF4G activates the transcription of SE-controlled lncRNA-DAW and promotes tumor growth by activating Wnt/β-catenin pathway in HCC." (PMID 38438958, 2024). "The GA3055 tumor contained an HNF4G-RSPO2 fusion between RSPO2 exon 2 and HNF4G exon 3 (NM_001330561.1)." (PMID 30250044, 2018). "Hepatocyte Nuclear Factor 4-gamma (HNF4G) is an orphan nuclear receptor superfamily involved in intestinal epithelial cell differentiation and function, which might promote tumor growth and invasion by inhibiting apoptosis." (PMID 41440381, 2025). "In support of this, X-ray crystallographic structures of HNF4G have revealed a common long-chain fatty acid, palmitic acid, occupying the ligand-binding domain pocket of HNF4G in these structures and palmitic acid has previously been shown to influence PDAC tumor growth and metastatic potential." (PMID 41168397, 2025). "The findings show that FOXA1 cobinds with HNF4G in the classical subtype of PDAC, but that FOXA1 is not a PF in this PDAC subtype and, instead, the key transcription factor driving primary tumor growth appears to be HNF4G." (PMID 41168397, 2025). "FOXA1 could bind to active enhancers in PDAC (in primary tumor tissue and the various models) at the same places as HNF4G; we could not observe a role for FOXA1 in mediating chromatin accessibility, gene expression or cell viability in primary tumor contexts." (PMID 41168397, 2025).
cancer (11 papers, 2018 to 2025). A tumor composed of atypical neoplastic, often pleomorphic cells that invade other tissues. "Oncogenes ATF1 and HOXA11, and HNF4G have been implicated in multiple cancers and are involved in the positive regulation of the RNA metabolic process." (PMID 35008416, 2022). "Next, to directly explore the role of FOXA1 and/or HNF4G in metastasis, engineered human cancer cell lines (HPAF-II) were injected into the tail vein of mice to directly assess metastatic potential." (PMID 41168397, 2025). "LGR5+ stem cells, like cancer cells, fail to express HNF4G and BTNL molecules, making crypt regions and tumors immune privileged sites, devoid of γδIELs." (PMID 37309673, 2023). "In this model, nuclear HNF4A expression was evident in cancer cells (albeit weak expression), whereas HNF4G and Btnl1 expressions were lost from tumors." (PMID 37309673, 2023). "Several studies have suggested that HNF4G might act as an oncogene modulating cell proliferation and invasion in cancer." (PMID 32737864, 2021). "Interestingly, NR3C2, PGR, RORA were differentially expressed in all 16 cancer types, while HNF4G was differentially expressed in only 5/16 cancers (31.3%)." (PMID 32024906, 2020). "Immunohistochemistry (IHC) analysis of FOXA1, HNF4A and HNF4G from primary PDAC tissue samples confirmed coexpression of these transcription factors, only in the cancer epithelial cells." (PMID 41168397, 2025). "MALAT1 has been found to promote cell proliferation and migration of cancer cells by regulating the expression of genes promoting metastases, e.g., RASSF6, HNF4G, CA2, ROBO1, MIA2." (PMID 35887000, 2022). "We found that HNF4A and HNF4G were completely absent from cancer cells, whereas normal adjacent epithelial cells maintained nuclear HNF4A and HNF4G staining." (PMID 37309673, 2023).